COMT (catechol-O-methyltransferase)
Diseases named in the same sentence as COMT in open-access papers (continued):
Sharing a sentence is not in itself a finding about the gene and the disease.
breast cancer (64 papers, 2001 to 2025). A primary or metastatic malignant neoplasm involving the breast. "A study investigating chemotherapy-induced cognitive impairment in breast cancer patients identified a potential association between the COMT (rs165599) polymorphism and cognitive decline in breast cancer survivors." (PMID 38689006, 2024). "The current research aimed to evaluate the regulation of the risk by COMT genotype on CRCI in breast cancer survivors with disparate status of HER2." (PMID 35211407, 2022). "The results of this study are innovative in that they represent the first demonstration of a link between a risk factor for CRCI and COMT genotype in breast cancer patients with the disparate status of HER2." (PMID 35211407, 2022). "In the present study, OPRM1 and COMT polymorphisms demonstrated a prognostic impact in breast cancer, significantly affecting overall survival at 30 years." (PMID 35198317, 2022). "Prior research also reports a survival impact of COMT polymorphisms on patients diagnosed with breast cancer, thus conferring a prognostic significance to the genetic mutation." (PMID 35198317, 2022). "Another study also found a correlation between COMT polymorphisms and breast cancer risk in postmenopausal women." (PMID 35198317, 2022). "A meta-analysis confirmed an increased incidence of breast cancer in the Asian population with COMT polymorphism, despite inconsistent previous results." (PMID 35198317, 2022). "Genetic polymorphisms in the mu-opioid receptor (OPRM1) and catechol-o-methyltransferase (COMT) genes have been shown to increase breast cancer risk." (PMID 35198317, 2022). "In our study, the genetic polymorphisms of OPRM1 and COMT affected the overall survival of breast cancer patients." (PMID 35198317, 2022). "The genetic polymorphisms of OPRM1 and COMT affected the overall survival of breast cancer patients, in concordance with previous research." (PMID 35198317, 2022). "Nevertheless, the motivation of COMT polymorphisms in regulating cognitive impairment in breast cancer survivors with disparate status of human epidermal growth factor receptor 2 (HER2) was still vague." (PMID 35211407, 2022). "Women with high BMI and the COMT (Met/Met) genotype demonstrated high breast cancer risk (odds ratio (OR) = 5.7; 95% CI 1.1–30.1)." (PMID 34462889, 2021). "As the COMT gene is an estrogen-metabolizing enzyme, polymorphisms have been postulated to impact breast cancer risk, with catechol estrogens having proposed oncogenic influence." (PMID 33731765, 2021). "Previous reports have shown that polymorphisms of COMT played a role in the risk of esophageal cancer, lung cancer, breast cancer, prostate cancer, and bladder cancer." (PMID 34209963, 2021). "In Taiwanese women it was observed that of the three gens, i.e., CYP17, CYP1A1, and COMT, low activity of the COMT genotype was associated with the highest relative risk of breast cancer (RR = 4.0; 95% CI 1.12–19.8)." (PMID 34462889, 2021). "In a study of pre-menopausal women, a significantly higher risk for breast cancer with COMT(Met/Met) genotypes, compared with the homozygotes COMT(Val/Val) genotype women, was revealed." (PMID 34462889, 2021). "The relationship between functional polymorphisms in COMT and the risk of breast cancer is investigated by numerous studies all over the world." (PMID 33282008, 2020). "In particular, the val108met COMT polymorphism, which results in a 3-4-fold decrease in activity, is associated with increased breast cancer risk." (PMID 32085420, 2020). "In an earlier study, the presence of homozygous high-risk alleles in three genes, i.e., CYP17, CYP1A1, COMT, have been shown to influence the development of breast cancer." (PMID 31980012, 2020). "The association of COMT Val158Met with cognitive impairment in breast cancer survivors has only been successfully replicated in patients with brain tumors." (PMID 30382534, 2019).
breast cancer (continued). "Nevertheless, COMT genetic variation has been linked to the age of onset of canine mammary carcinomas, to the development of high-grade mammary carcinomas, vascular invasion and recurrences." (PMID 31506083, 2019). "It was reported that catechol-O-methyltransferase involves in breast cancer and estrogen-linked endometrial cancers due to their cancer-promoting activities." (PMID 27027344, 2017). "The COMT gene regulates expression of catechol-O-methyltransferase (COMT) enzymes, which metabolize dopamine, norepinephrine, and epinephrine; several SNPs in the COMT gene have been associated with symptoms in breast cancer patients and survivors." (PMID 28616125, 2017). "The low activity of COMT, associated with the mutant allele L, was linked to both benign and malignant disease, such as endometriosis, endometrial cancer, and breast cancer." (PMID 26798414, 2016). "Green tea-drinking women with the homozygous AA genotype of COMT have been shown to have a lower risk of breast cancer." (PMID 27074016, 2016). "Methylation at several of these loci also associated with COMT gene expression in breast cancer cell lines." (PMID 24460628, 2014). "Epidemiological study data on the influence of the variant COMT (Met/Met) with human breast cancer are controversial." (PMID 24629213, 2014). "One meta-analysis of COMT Val158Met based on more than 30,000 cases and 38,000 controls, found an increased risk for breast cancer only when the sample was stratified by race." (PMID 24460628, 2014). "Many epidemiological studies have been conducted to explore the association between the COMT Val158Met polymorphism and breast cancer risk." (PMID 23039364, 2012). "In an effort to shed some light on the impact of COMT Val108/158Met polymorphism on breast cancer risk, two previous meta-analyses were conducted almost at the same time to explore the relationship between COMT Val108/158Met polymorphism and breast cancer." (PMID 23039364, 2012). "They concluded that COMT Val158Met polymorphism was significantly associated with increased breast cancer risk in European population." (PMID 23039364, 2012). "Next, the effect of COMT Val158Met polymorphism on breast cancer risk was evaluated according to ethnicity, menopausal status and sources of controls." (PMID 23039364, 2012). "Thirty of the studies were population-based case–control studies and 20 were hospital-based studies, four of these studies presented COMT Val158Met polymorphism genotype distributions according to family history (familial-based breast cancer)." (PMID 23039364, 2012). "Human studies have suggested that high-activity CYP1B1 alleles and low-activity COMT alleles are associated with increased risk of breast cancer and other E2-responsive cancers." (PMID 20435547, 2010). "In this study, we have shown a combined effect between the two commonly occurring polymorphisms associated with higher enzymatic activity of CCND1 and COMT in the context of breast cancer predisposition." (PMID 18194538, 2008). "In Ontario, the heterozygote (medium activity) [OR: 1.66, 95%CI (1.18–2.33)] and high activity [OR: 2.22, 95%CI (1.49–3.28)] combinations of CCND1 and COMT genotypes showed statistically significant association with increased breast cancer risk." (PMID 18194538, 2008). "In this study, we have investigated the contribution of independent and the combined effects of CCND1 Pro241Pro and COMT Met108/158Val polymorphisms to breast cancer risk in two independent Caucasian populations from Ontario and Finland." (PMID 18194538, 2008). "Using two independent Caucasian populations, we have shown a stronger combined effect of the two commonly occurring CCND1 and COMT genotypes in the context of breast cancer predisposition." (PMID 18194538, 2008). "In order to assess the association of COMT genotypes with breast cancer risk, we have carried out a meta-analysis." (PMID 18194538, 2008).
breast cancer (continued). "Our results suggest a genetic cross-talk between the medium and higher enzymatic activity allele combinations of CCND1 and COMT in breast cancer development." (PMID 18194538, 2008). "Larger studies with the ability to look at interactions would be useful to elucidate the influence of genetic variation in CYP1A2 and COMT on the risk of developing breast cancer." (PMID 17295924, 2007). "This cross-sectional analysis examined the relation between mammographic density and the CYP1A2*1F and COMT Val58 Met polymorphisms among 332 breast cancer cases and 254 controls in the Hawaii component of the Multiethnic Cohort." (PMID 17295924, 2007). "No study has examined the associations of polymorphisms in CYP1A1, CYP1B1, and COMT with breast cancer risk among women with BBD." (PMID 16808847, 2006). "Only a few studies have assessed potential modification by cigarette smoking on the risk of breast cancer for women with COMT-LL as compared to COMT-HH." (PMID 16417624, 2006). "Four earlier studies have examined the association between COMT activity and the risk of breast cancer within sub-groups of tobacco exposure." (PMID 16417624, 2006). "The relative risk of breast cancer among women with the COMT-HL or COMT-HH genotype who were actively or passively exposed to tobacco smoke for a long duration was higher than expected from the independent effects of the genotype and smoking exposure." (PMID 16417624, 2006). "The relative risk of breast cancer for women with the COMT-HL genotype and a history of ever-active smoking was 1.6-fold (95% CI: 0.7, 3.8) higher than the product of the relative risks associated with the genotype alone and smoking alone." (PMID 16417624, 2006). "This variability in methyltransferase activity related to the polymorphism has prompted research investigating the association between COMT genotype and breast cancer risk." (PMID 16417624, 2006). "This large case-only analysis is only the second to investigate the interaction between COMT genotype and exposure to tobacco smoke as related to breast cancer risk while removing women passively exposed to tobacco smoke from the reference group." (PMID 16417624, 2006). "Increased oxidative DNA damage has been detected in target tissues after exposure to estrogen, and a low-activity form of catechol-O-methyltransferase has been associated with an increased risk of breast cancer." (PMID 16417649, 2006). "Previous studies of the association between COMT genotype and breast cancer risk have compared women with one or more copies of the polymorphism to a reference group of women homozygous for the wild-type allele." (PMID 16417624, 2006). "In fact, menopausal effects on breast cancer risk have also been observed in a previous study investigating genetic polymorphisms in catechol-O-methyltransferase." (PMID 16168120, 2005). "In the current research, we attempt to survey the chemotherapy-related PM impairment in breast cancer survivors with different HER2 and clear cut the genetic features of COMT polymorphisms on CRCI in breast cancer patients with the disparate status of HER2 (HER2−, HER2+)." (PMID 35211407, 2022). "Breast cancer is a tumor closely associated with estrogen, and estrogen could downregulate the level of COMT gene, decreasing the activity of COMT enzyme." (PMID 35211407, 2022). "For example, genetic variations in COMT may influence the risk of breast cancer as a result of significant changes in catechol estrogen and methoxyestrogen levels." (PMID 35664769, 2022). "The COMT SNP encodes a low activity that plays a potential role in the risk of breast cancer." (PMID 34209963, 2021). "Polymorphism in the COMT gene resulted in a 40% decrease in enzymatic activity and this may modify the relationship between breast cancer risk and green tea consumption." (PMID 32823812, 2020).
breast cancer (continued). "Furthermore, some variants in estrogen-related genes, such as CYP1A1 T3801C, CYP1A1 A2455G, and COMT Val158Met, were identified as susceptibility loci in breast cancer development according to recent meta-analysis reports." (PMID 25689428, 2015). "Finally, we tested associations between COMT CpG methylation state and COMT gene expression in breast cancer cell lines." (PMID 24460628, 2014). "In addition, we were able to test for associations between COMT DM and observed variation in COMT gene expression in breast cancer cell lines." (PMID 24460628, 2014). "First, some studies found significant associations between COMT Val108/158Met polymorphism and breast cancer risk in several subgroups of populations, such as associations among postmenopausal women with a low body mass index (BMI), a high BMI or women at young ages." (PMID 23039364, 2012). "It has been hypothesized that individuals who inherit the low activity COMT gene may be at increased risk for breast cancer because of an increased accumulation of the catechol estrogen intermediates." (PMID 23039364, 2012). "The inconsistent relationships between CYP1B1, COMT, and breast cancer risk seen across epidemiology studies may reflect divergent risk associated with variable environmental E2 exposures." (PMID 20435547, 2010). "Until larger studies with the ability to look at gene-gene and gene-environment interactions are completed, it will remain unclear to what extent the variant alleles for CYP1A2 and COMT affect a woman's lifetime risk of developing breast cancer." (PMID 17295924, 2007). "A few studies have found an elevated breast cancer risk for women with low COMT activity." (PMID 16417624, 2006). "It is therefore possible that previous studies evaluating the interaction of COMT genotype and exposure to tobacco smoke in relation to breast cancer risk may have generated biased estimates of interaction." (PMID 16417624, 2006). "The heterogeneity of CRCI may be rectified by COMT (rs165599, rs737865) polymorphism, and this rectification may possibly show that COMT polymorphism is a risk leading to a lower memory performance in breast cancer patients with disparate HER2." (PMID 35211407, 2022). "It has been assesed that individuals who inherit the low activity COMT gene may be at increased risk for breast cancer, because of an increased accumulation of the catechol estrogen intermediates, clearing the pathogenic pathway of developing breast cancer." (PMID 23659667, 2013). "Polymorphisms in several hormone pathway genes, including CYP19A1 and COMT, have been associated with endogenous hormone levels; however, studies investigating the association of genetic variation in hormone metabolism genes and breast cancer risk have generated mixed results." (PMID 21457551, 2011). "Thus these evidences support the role of high COMT activity in breast cancer susceptibility." (PMID 18194538, 2008). "We hypothesized that women who have low COMT activity and are exposed to tobacco smoke should have an enriched concentration of 2-hydroxylated catechol estrogen, and should therefore have a lower smoking-related risk of breast cancer than women with high COMT activity." (PMID 16417624, 2006). "In a study of patients with breast cancer, compared to patients with the GG genotype for COMT rs165599, patients with the GA and AA genotypes had a lower odds of developing self-reported cognitive decline." (PMID 39325169, 2025). "Three studies have explored the relationship between catechol-O-methyltransferase (COMT) and fatigue in breast cancer patients." (PMID 39372868, 2024). "Recently, we found that COMT (rs737865) was correlated to EBPM in breast cancer patients with different hormonal receptor expression." (PMID 35211407, 2022). "Further study found that COMT (rs737865) was correlated with EBPM damage following chemotherapy in breast cancer with different expressions of hormone receptor." (PMID 35211407, 2022).
breast cancer (continued). "Estrogen enhanced the promoters of DNMT3B, MBD2, and HDAC1 in breast cancer cells and reduced COMT transcription, resulting in increased DNA oxidative damage." (PMID 35211407, 2022). "Population frequencies of COMT haplotypes are well described in several pain-related studies predominantly of Caucasian ancestry, and in non-breast cancer studies." (PMID 36672750, 2022). "Older studies have demonstrated a higher breast cancer incidence in women with lower COMT enzymatic levels." (PMID 35198317, 2022). "HAT can significantly increase the expression of the Catechol-O-Methyltransferase (COMT) gene, which is a risk factor for breast cancer, and inhibit the survival of MCF-7 breast cancer cells stimulated by estrogen." (PMID 33193750, 2020). "The methylation of EGCG by catechol-O-methyltransferase (COMT) was less bio-effective in breast cancer MDA-MB-231 cells." (PMID 33113766, 2020). "Many studies have evaluated the association between SNPs in estrogen-related genes, such as CYP17, CYP19, CYP1A1, CYP1B1, COMT, GSTP1, and ERα/β, and the risk of breast cancer, especially in postmenopausal women." (PMID 25689428, 2015). "In the past decade, the findings about the relationship between Catechol-O-methyltransferase Val158Met (COMT Val108/158Met) polymorphism and breast cancer risk were inconsistent." (PMID 23635316, 2013). "Due to the complementary functional roles of COMT and CCND1, we have also investigated the combined effect of their genotypes in association with altered breast cancer risk." (PMID 18194538, 2008). "In the combined analysis, the higher activity alleles of the COMT and CCND1 is associated with increased breast cancer risk in both Ontario [OR: 2.22, 95%CI (1.49–3.28)] and Finland [OR: 1.73, 95%CI (1.08–2.78)] populations studied." (PMID 18194538, 2008). "The allele frequencies for COMT and CCDN1 polymorphisms in the breast cancer populations of both Finland and Ontario was 0.45 and 0.51 for COMTHigh(Val), and 0.50 and 0.49 for CCND1High (A), respectively." (PMID 18194538, 2008). "The magnitude of the increased combined risk effect was higher in Ontario compared to Finland; however a test for trend supported the association of increased breast cancer risk with increasing activity of both CCND1 and COMT genotypes in both populations." (PMID 18194538, 2008). "Our findings suggest that COMT and CCND1 alleles act in combination and contribute to breast cancer progression." (PMID 18194538, 2008). "Multivariate analyses revealed several statistically significant SNP-SNP interactions associated with increased breast cancer risk including one between CCND1 Pro241Pro and COMT Met108/158Val polymorphisms." (PMID 18194538, 2008). "By using a more accurate genotyping method and by implementing a case-only design, this analysis provides a more valid assessment of departure from multiplicative interaction between COMT genotype and exposure to tobacco smoke in relation to breast cancer." (PMID 16417624, 2006). "The aim of the present study was to analyze the associations between genetic polymorphisms in three estrogen metabolizing enzymes (COMT, CYP1A1, CYP1B1) and the two estrogen receptors (ESR1, ESR2) and the risk of developing breast cancer among women with BBD." (PMID 16808847, 2006). "In a recent breast cancer case -control study, including categorical values only (genotypes), a four-locus susceptibility model including the polymorphisms of COMT, CYP1A1m1, CYP1B1 codon 48, and CYP1B1 codon 432 was found associated with breast cancer." (PMID 16412218, 2006). "This investigation is the largest case-only study to date to examine the interaction between COMT genotype and tobacco exposure history as it relates to breast cancer." (PMID 16417624, 2006).